MAP1S (microtubule associated protein 1S)
Diseases named in the same sentence as MAP1S in open-access papers (continued):
Sharing a sentence is not in itself a finding about the gene and the disease.
prostate adenocarcinoma (1 paper, 2016). "Previously, we reported that MAP1S suppresses hepatocellular carcinogenesis in a mouse model and promoted the survival of patients with prostate adenocarcinomas by increasing the degradation of aggregated proteins and dysfunctional mitochondria." (PMID 26701856, 2016). "It has been reported that high levels of MAP1S predict better prognosis for patients suffering from prostate adenocarcinomas." (PMID 26701856, 2016). "MAP1S levels were increased in response to the initiation and development of human prostatic adenocarcinomas (PCA), but subsequent loss of MAP1S expression in PCA patients led to shortening of their overall survival." (PMID 26701856, 2016).
Renal atrophy (1 paper, 2016). Atrophy of the kidney. "Here, we observed that the levels of MAP1S in renal tissues from patients with renal atrophy and renal failure are dramatically reduced." (PMID 27236336, 2016). "The levels of MAP1S were dramatically reduced and levels of fibronectin were greatly elevated in renal fibrotic tissues from patients diagnosed as renal atrophy and renal failure." (PMID 27236336, 2016).
renal cell carcinoma (1 paper, 2016). "The levels of MAP1S in normal renal cells are dramatically higher than those in the ccRCC tissues and cell lines derived from renal cell carcinomas." (PMID 26701856, 2016).
tumor (14 papers, 2008 to 2022). "Knockdown of MAP1S almost completely abrogated the inhibition of tumor growth and migration by flagellin treatment, which is consistent with a previous report showing that MAP1S deficient mice frequently develop tumors." (PMID 24466264, 2014). "The combination of high expression of LRPPRC and low expression of MAP1S can inhibit autophagy and promote tumor development." (PMID 34745261, 2021). "Because of close relation between autophagy and tumorigenesis and because the RASSF1A-interactive protein MAP1S is involved in autophagy regulation and tumor suppression, we reasoned that RASSF1A regulates autophagy and suppresses tumorigenesis." (PMID 30315205, 2019). "The examination of ccRCC tissues with high levels of MAP1S in detail revealed that the staining of MAP1S in clear cells were much weaker than other cells in the tumor focus (Insert)." (PMID 26701856, 2016). "The same trends were confirmed by immune-florescent staining: the intensities of MAP1S in normal tissues were the highest, tissues adjacent to tumors the second, and tumor tissues the lowest." (PMID 26701856, 2016). "If the autophagy flux is blocked, more malignant tumor will develop in a similar way as we reported in the MAP1S knockout mice." (PMID 26571030, 2015). "Here, we tested the role of MAP1S in tumor suppression induced by these soluble factors in a co-culture Transwell system." (PMID 24466264, 2014). "Remarkably, MAP1S played a critical role in tumor suppression induced by flagellin, and knockdown of MAP1S almost completely abrogated the suppression of tumor growth and migration by flagellin treatment." (PMID 24466264, 2014). "In the late stage of TLR5-induced inflammation, elevated MAP1S negatively regulated the tumor microenvironment to inhibit inflammation and induced autophagy to suppress tumorigenesis." (PMID 24466264, 2014). "In response to the high requirement of autophagy activity, MAP1S is elevated in such tumor foci." (PMID 26750654, 2016). "In addition, elevated expression of MAP1S in response to flagellin feed-back regulated tumor inflammatory microenvironment in the late stages of TLR5 signaling through degradation of MyD88 in autophagy process." (PMID 24466264, 2014). "The promotion of autophagy by MAP1S reduces genomic instability to suppress tumor development in hepatocarcinoma, and MAP1S may also co-ordinate mitochondrial dynamics and autophagy." (PMID 24995158, 2014). "We also found MAP1S played a critical role in tumor suppression induced by flagellin treatment." (PMID 24466264, 2014). "Furthermore, expression of four proteins is associated with tumor progression/high risk AML: DOT1L, mTOR, VIM and ZNF521, whereas the expression of six proteins is associated with tumor suppression/low risk AML: AEBP2, CAST, CBFB, LSP1, MAP1S and probably PCBP1." (PMID 30634713, 2019). "It will be essential to determine associations of RASSF1A polymorphisms with key cell death mediators, such as MOAP-1, TNF-R1, DAPK, C19ORF5/MAP1S, and MST1/2 in order to ascertain their importance in influencing the tumor suppressor function of RASSF1A." (PMID 22701175, 2012). "If tumor cells are not capable of providing sufficient MAP1S to promote autophagy flux to meet the demand, they may induce pyroptosis to impair the survival of themselves and their host cells." (PMID 26750654, 2016).
cancer (4 papers, 2014 to 2016). A tumor composed of atypical neoplastic, often pleomorphic cells that invade other tissues. "Thus, MAP1S controls the TLR5 signaling pathway in cancer cells." (PMID 24466264, 2014).
neurodegenerative disease (1 paper, 2023). A disorder of the central nervous system characterized by gradual and progressive loss of neural tissue and neurologic function. "It has been suggested that defects in MAP1S-regulated programmed cellular destruction (autophagy) could impact neurodegenerative diseases." (PMID 37510383, 2023).
neurological disorders (1 paper, 2025). "Our discovery that MAP1S phosphorylation modulates proteolytic processing during neural development suggests that this mechanism may be disrupted in neurological disorders." (PMID 41000643, 2025). "In this study, we uncover a new layer of microtubule regulation by microtubule binding proteins, in which we identify Microtubule Associated Protein (MAP)1S as a novel substrate of Ser-Arg Protein Kinase (SRPK), which is itself implicated in neurological disorders." (PMID 41000643, 2025). "Therefore, dysregulation of MAP1S function could be at least partially responsible for etiology or neurological diseases via microtubule cytoskeleton dysfunction." (PMID 41000643, 2025).
MAP1S also shares sentences with these, for which no sentence is quoted: adenocarcinoma (1 paper); Cirrhosis (1); COVID-19 (1); gastric cancer (1); liver cancer (1); lymph node metastasis (1); meningioma (1); non-small cell lung carcinoma (1); renal failure (1); squamous cell carcinoma (1).